METTL3 (methyltransferase 3, N6-adenosine-methyltransferase complex catalytic subunit)
Diseases named in the same sentence as METTL3 in open-access papers (continued):
Sharing a sentence is not in itself a finding about the gene and the disease.
tauopathy (2 papers, 2023 to 2025). Neurodegenerative disorders involving deposition of abnormal tau protein isoforms (tau proteins) in neurons and glial cells in the brain. "To explore the therapeutic potential of targeting excessive m6A RNA accumulation, we examined the effects of STM2457, a selective METTL3 inhibitor, on AD-related pathology in P301S PS19 tauopathy mice." (PMID 41510223, 2025).
thymic carcinoma (2 papers, 2021 to 2022). Thymic carcinoma (TC) is a type of thymic epithelial neoplasm characterized by a high malignant potential. "In this work, we assessed that METTL3 is upregulated in thymic tumors and we investigated the biological significance of the increased levels of METTL3 in thymic carcinoma cells." (PMID 34530916, 2021). "For this reason, we analyzed and established a sensitization effect of thymic carcinoma cells to a chemotherapeutic agent, like cisplatin, upon METTL3 silencing." (PMID 34530916, 2021). "Silencing of METTL3 expression in thymic carcinoma cells results in reduced cell proliferation and overall translation rate." (PMID 34530916, 2021). "Recently, the expression of MALAT1 has been a focus in our studies where the relationship between lncRNA MALAT1 and METTL3, a methyltransferase enzyme that catalyzes the N6-methyladenosine (m6A) modification, were described in the thymic carcinoma cell line, TC1889." (PMID 35529877, 2022). "Consistent with these evidences, we validated c-MYC as target of METTL3-dependent methylation also in Thymic carcinoma and showed the requirement of METTL3 for an efficient c-MYC expression in TC1889 cells, suggesting that METTL3 might enhance cell proliferation by promoting c-MYC translation." (PMID 34530916, 2021). "To investigate the biological output of the high expression level of METTL3 in TET, we depleted METTL3 by siRNA transfection in the thymic carcinoma cell line TC1889, to evaluate the effects on proliferation and colony forming ability." (PMID 34530916, 2021). "Interestingly, analysis of METTL3 protein staining intensity in epithelial cancer cells revealed an increase of intensity from types A/AB (score of intensity = 1) to types B1-B3 (score of intensity = 2), and reached a maximum of intensity (score = 3) in thymic carcinoma cases (C)." (PMID 34530916, 2021). "Bioinformatic analysis of TGCA data showed a positive correlation between METTL3 and c-MYC mRNA levels in Thymoma and Thymic carcinoma samples." (PMID 34530916, 2021). "In thymoma and thymic carcinoma, MALAT1 regulates cell proliferation by acting as an miR-145-5p sponge and contributing to c-MYC induction, following its change in subnuclear localization due to METTL3 methylation." (PMID 35529877, 2022).
thymic epithelial tumors (2 papers, 2021 to 2024). "METTL3 is highly expressed and was identified as a carcinogen in thymic epithelial tumors." (PMID 38331776, 2024).
ulcerative colitis (2 papers, 2023 to 2025). An inflammatory bowel disease involving the mucosal surface of the large intestine and rectum. "Here, we show that methyltransferase-like 3 (METTL3) expression is downregulated in the colon mucosa in ulcerative colitis (UC) patients and strongly associated with the differentiation and maturation of goblet cells during inflammation." (PMID 39762134, 2025). "To explore the potential role of METTL3 in the pathogenesis of IBD, we further analyzed its expression in intestinal mucosa from patients with ulcerative colitis (UC) and healthy controls based on database (GSE179128)." (PMID 39762134, 2025).
uveitis (2 papers, 2022 to 2025). An inflammatory process affecting a part of or the entire uvea. "In summary, the effect of METTL3 in uveitis varies depending on cell type and experimental conditions." (PMID 41315216, 2025). "Therefore, differences in cell types and experimental conditions must be thoroughly considered when investigating METTL3’s role in uveitis to gain a comprehensive understanding of its mechanism in disease development." (PMID 41315216, 2025). "In addition, these decreased METTL3 expression in RPE cells of EAU or endotoxin induced uveitis (EIU) mice is contrary to the in vitro findings, which revealed a complex process with various cells interaction of the in vivo models." (PMID 35936005, 2022).
acral melanomas (1 paper, 2021). "Further molecular mechanism investigation indicated that TXNDC5 was downregulated by decreasing m6A-levels after METTL3 knockdown and ultimately inhibiting the progression of primary acral melanoma." (PMID 35117988, 2021). "The high expression of METTL3 was positively related to advanced clinical stage in primary acral melanoma." (PMID 35117988, 2021). "METTL3 was essential for acral melanoma carcinogenesis and progression, as featured by promoting cancer cell proliferation, migration, and invasion." (PMID 35117988, 2021). "Correlation between METTL3 expression and clinicopathologic features of acral melanoma patients (n = 34)." (PMID 35117988, 2021). "Nevertheless, not much is known about the biological and pathological role of METTL3-dependent m6A modification in acral melanoma." (PMID 35117988, 2021). "In conclusion, we revealed the critical role of METTL3-mediated m6A modification in acral melanoma progression; increased m6A level was confirmed in acral melanoma samples." (PMID 35117988, 2021). "We then confirmed that METTL3 functions as an oncoprotein in primary acral melanoma by both in vitro and in vivo experiments." (PMID 35117988, 2021). "Besides, higher expression of METTL3 messenger RNA (mRNA) correlated with a higher stage in primary acral melanoma patients." (PMID 35117988, 2021). "As such, our findings support the use of METTL3 as a biomarker of acral melanoma initiation." (PMID 35117988, 2021). "We also found that TXNDC5 served as a novel target of METTL3-m6A axis in acral melanoma." (PMID 35117988, 2021). "Thus, identification in their specimens from primary sites suggested specific changes in m6A modification and methyltransferase METTL3 levels occurring in the early stages of acral melanoma pathogenesis." (PMID 35117988, 2021).
acute liver failure (1 paper, 2024). Rapid deterioration of liver function causing encephalopathy and coagulopathy. "In this study, we explored the potential reasons why hepatocyte-specific METTL3 homozygous disruption by Alb-iCre mice (GPT), but not by Alb-Cre mice (JAX), resulted in acute liver failure (ALF) and then postnatal lethality." (PMID 38656880, 2024).
acute promyelocytic leukemia (1 paper, 2025). An aggressive form of acute myeloid leukemia (AML), characterized by arrest of leukocyte differentiation at the promyelocyte stage, due to a specific chromosomal translocation t(15;17) in myeloid cells. "The process of lactylation significantly increases the expression of Methyltransferase-like 3 (METTL3), thereby enhancing the resistance of acute promyelocytic leukemia to all-trans retinoic acid (ATRA)." (PMID 41179284, 2025).
airway hyperresponsiveness (1 paper, 2023). "Furthermore, compared to WT mice, airway hyperresponsiveness (AHR) during the methacholine challenge was exaggerated in CRE-sensitized Mettl3 KO animals." (PMID 37957139, 2023).
ameloblastoma (1 paper, 2024). The most common odontogenic tumor, arising from the epithelial component of the embryonic tooth and usually affecting the molar-ramus region of the mandible or maxilla. "This study aimed to investigate the expression of METTL3 expression in dental follicles (DF), dentigerous cysts (DC), unicystic ameloblastoma (UA), and conventional ameloblastoma (conventional AM) using immunohistochemistry." (PMID 39822792, 2024). "This study aimed to examine METTL3 expression in dental follicles (DF), dentigerous cysts (DC), unicystic ameloblastoma (UA), and conventional ameloblastoma (conventional AM)." (PMID 39822792, 2024).
anemia (1 paper, 2026). A reduction in the number of red blood cells, the amount of hemoglobin, and/or the volume of packed red blood cells. "In this study, we found that deletion of Mettl3 using the EpoR-Cre mouse led to microcytic/hypochromic anemia due to defective erythropoiesis along with impaired hemoglobin biosynthesis." (PMID 41805631, 2026).
Anxiety (1 paper, 2023). Intense feelings of nervousness, tension, or panic often arise in response to interpersonal stresses. "Moreover, it has also been revealed that METTL3 knockout significantly hypermethylated genes in the AMY, which regulate behavioral and hormonal stress responses, fear, and anxiety." (PMID 37189411, 2023). "Moreover, the study reported that neither deletion of METTL3 nor FTO in mice showed altered anxiety-like behavior or locomotion, but we observed significant changes in spontaneous digging behavior." (PMID 37189411, 2023).
Aortic dissection (1 paper, 2025). Aortic dissection refers to a tear in the intimal layer of the aorta causing a separation between the intima and the medial layers of the aorta. "More importantly, overexpression of METTL3 in HASMCs promoted erastin- and cystine deprivation-induced ferroptosis, while knocking down METTL3 increased both SLC7A11 and FSP1 expression and reduced ferroptosis, suggesting that ferroptosis plays a crucial pathogenic role in aortic dissection." (PMID 40000618, 2025).
bacterial pneumonia (1 paper, 2024). Acute infection of the lung parenchyma caused by bacteria (e.g., Streptococcus pneumoniae, Haemophilus influenzae, Chlamydia pneumoniae, Mycoplasma pneumoniae, and Legionella pneumophila). "This investigation elucidated the effect of METTL3 on SP‐induced AECs and explored the downstream pathways of METTL3 to provide a new theoretical basis for the treatment of bacterial pneumonia." (PMID 38757482, 2024). "Furthermore, the revealed mechanism of the METTL3/NEAT1/CTCF/MUC19 axis provides new theoretical knowledge for bacterial pneumonia treatment and furnishes evidence for future therapeutic direction." (PMID 38757482, 2024). "As a m6A methyltransferase, METTL3 essentially regulates different target genes via m6A methylation; therefore, these downstream genes should be elucidated to unveil the comprehensive molecular landscape of bacterial pneumonia." (PMID 38757482, 2024).
bacterial Sepsis (1 paper, 2025). "Targeting methylation-modifying enzymes, such as METTL3, METTL4, and DNMT1, provides a promising therapeutic strategy to regulate gene expression, alleviate AEC dysfunction, and slow the progression of bacterial Sepsis-Associated ALI." (PMID 40842982, 2025). "During bacterial Sepsis-Associated ALI, NETs regulate AEC functionality and disease pathogenesis through TLR9 pathway activation, which subsequently modulates METTL3-dependent methylation patterns." (PMID 40842982, 2025). "In the context of bacterial sepsis, lactate and NETs upregulate METTL3 expression by activating p300 histone acetyltransferase-mediated enhancer modifications (H3K27ac and H3K18la)." (PMID 40842982, 2025).
bile duct cancer (1 paper, 2018). "In colorectal, prostate and bile duct cancers, METTL3 has been reported to be significantly upregulated based on bioinformatic analysis." (PMID 30062093, 2018).
bone metastasis (1 paper, 2023). Transfer of a neoplasm from its primary site to bones. "Future studies would benefit from expanding sample sizes in a multicenter environment to establish a clearer relationship between the expression of METTL3, YTHDF1, ANLN and bone metastasis." (PMID 36923927, 2023).
bone tumors (1 paper, 2025). "In U2OS cells, knockdown of METTL3 induces widespread AS alterations involving 1,803 genes, which are enriched in cell cycle-related pathways, suggesting that METTL3 may play a critical role in cell cycle control of bone tumors through AS regulation." (PMID 41268214, 2025).
brain glioma (1 paper, 2023). A malignant glioma that involves the brain. "Silencing METTL3 in brain glioma stem cells was observed to increase their sensitivity to γ-rays and block DNA repair, as demonstrated by the accumulation of γ-H2AX." (PMID 37522921, 2023). "Moreover, METTL3 silencing was found to rescue the formation of neurospheres, which further enhances the radiosensitivity of brain gliomas." (PMID 37522921, 2023).
breast ductal carcinoma (1 paper, 2023). "Mettl3 was highly expressed in breast ductal carcinoma tissues." (PMID 36609396, 2023).
Burkitt lymphoma (1 paper, 2022). A rare form of malignant mature B-cell non-Hodgkin lymphoma. "The viability and growth of EBV-positive Burkitt lymphoma Akata cells were suppressed by simultaneous anti-IgG treatment and m6A modification blockade, either by KO of METTL3 or by inhibitors of m6A modification." (PMID 35783391, 2022).
cataract (1 paper, 2025). Partial or complete opacity of the crystalline lens of one or both eyes that decreases visual acuity and eventually results in blindness. "Overall, while significant progress has been made in studies of m6A modification in cataracts, a consistent observation across different types of cataracts is that METTL3 promotes LEC apoptosis." (PMID 41315216, 2025).
Cerebral arteriovenous malformation (1 paper, 2022). "METTL3 plays a similar role in cerebral arteriovenous malformation, and deletion of METTL3 in ECs significantly affects angiogenesis by reducing heterodimeric Notch E3 ubiquitin ligase formed by DTX1 and DTX3L." (PMID 35001873, 2022).
Cholestatic liver disease (1 paper, 2025). "Collectively, our findings establish hepatocyte Mettl3 deficiency as a pivotal driver of PSC pathogenesis and highlight the therapeutic potential of targeting the m6A epitranscriptome in cholestatic liver diseases." (PMID 41431138, 2025).
choriocarcinoma (1 paper, 2024). An aggressive malignant tumor arising from trophoblastic cells. "Studies have shown that METTL3 contributes to the maturation of miR-21-5p in gestational choriocarcinoma." (PMID 38602536, 2024).
colon dysplasia (1 paper, 2025). A morphologic finding indicating the presence of dysplastic glandular epithelial cells in the colonic mucosa. "Surprisingly, compared with Mettl3-WT mice, colon dysplasia and loss of goblet cells were found in Mettl3-KO mice." (PMID 39762134, 2025).
corneal diseases (1 paper, 2021). "Our study identified METTL3 as a critical factor for corneal injury repair and suggested that manipulation of METTL3 and m6A modifications could be a promising therapeutic strategy for treating corneal diseases." (PMID 34721590, 2021).
coronary artery stenosis (1 paper, 2024). "This study aims to explore the association of methyltransferase-like protein 3 (METTL3) expression with severity of coronary artery stenosis in patients with coronary heart disease (CHD)." (PMID 39371395, 2024).
Crohn's colitis (1 paper, 2023). Crohn's disease affecting the colon. "Our study reveals that METTL3‐mediated m6A modification of circPRKAR1B promotes Crohn's colitis by aggravating NLRP3 inflammasome‐mediated pyroptosis via autophagy impairment in colonic epithelial cells." (PMID 37679886, 2023). "Our study reveals that circPRKAR1B upregulation, which is at least partially induced by METTL3‐mediated m6A modification, promotes Crohn's colitis by aggravating NLRP3 inflammasome‐mediated pyroptosis via autophagy impairment." (PMID 37679886, 2023).
cutaneous T-cell lymphoma (1 paper, 2025). "Previous studies have suggested that METTL3, a key m6A methyltransferase, inhibits the proliferation and migration of cutaneous T-cell lymphoma (CTCL) cells by regulating the expression of CDKN2A." (PMID 40332203, 2025). "This study aimed to elucidate the biological function and clinical relevance of the m6A methyltransferase METTL3 in cutaneous T-cell lymphoma (CTCL)." (PMID 40332203, 2025).
deafness (1 paper, 2024). An inherited or acquired condition characterized by the complete loss of the ability to hear from one or both ears. "Further research is warranted to delineate the precise role of METTL3 in the pathogenesis of deafness." (PMID 39193335, 2024).
dementia (1 paper, 2023). Loss of intellectual abilities interfering with an individual's social and occupational functions. "In this paper, the gene expression of METTL3 and NDUFA10 were found to correlate with the Mini-mental State Examination (MMSE), which is a clinical indicator of the degree of dementia." (PMID 37373264, 2023).
dry eye (1 paper, 2023). "The m6A expression level in pSS patients with dry eye was positively associated with increased METTL3 expression (r = 0.793, P value<0.001)." (PMID 37277716, 2023). "Our work revealed that the upregulation of m6A and METTL3 was associated with the performance of serological indicators and dry eye signs in pSS patients with dry eye." (PMID 37277716, 2023). "We observed a significant correlation of m6A and METTL3 expression with certain signs of dry eye when assessing tear secretion and ocular surface damage, which indicates that aberrant m6A modification may contribute to the pathogenesis of dry eye in pSS." (PMID 37277716, 2023). "Our work revealed that upregulation of m6A and METTL3 was related to the manifestation of serological indicators and dry eye signs in pSS patients with dry eye, which indicates that METTL3 may contribute to the pathogenesis of dry eye related to pSS." (PMID 37277716, 2023). "METTL3 may contribute to the pathogenesis of dry eye related to pSS." (PMID 37277716, 2023). "The relative mRNA and protein expression levels of the m6A regulators methyltransferase-like 3 (METTL3) and YT521-B homology domains 1 were markedly elevated in pSS patients with dry eye (both P value<0.01)." (PMID 37277716, 2023). "Our findings revealed that the expression level of the m6A modification and the mRNA and protein expression of METTL3 and YTHDF1 were all increased in pSS patients with dry eye." (PMID 37277716, 2023).
emphysema (1 paper, 2024). "Furthermore, the aberrant cross-talk between macrophages and bronchial epithelial cells is essential for the degradation of elastin which contributes to emphysema, in which METTL3 plays a critical role." (PMID 39416774, 2024). "Notably, METTL3 is critical for the aberrant cross-talk of epithelium-macrophages in emphysema and, thereby may be used in clinical diagnosis for emphysema." (PMID 39416774, 2024).
endometrial adenocarcinoma (1 paper, 2021). "For writers, the expression of METTL3 and RBM15/15B was significantly increased in patients with endometrial adenocarcinoma versus controls." (PMID 34149936, 2021). "Finally, we validated the mRNA expression of METTL3, FTO, RBM15, and YTHDF1 in clinical samples of endometrial tissues from endometrial adenocarcinoma patients and controls." (PMID 34149936, 2021). "We found that METTL3 and FTO mRNA expression was evidently decreased in endometrial adenocarcinoma while RBM15 mRNA expression was increased with no changes in YTHDF1 expression in cases versus controls." (PMID 34149936, 2021).
endometrioid ovarian cancer (1 paper, 2022). "A transcriptome m6A methylation analysis towards endometrioid ovarian cancer showed the influence of METTL3 on endometrioid ovarian cancer, and revealed the knockout of METTL3 resulted in distinct decrease of proliferation, increasing apoptosis, and G0/G1 blocking of cell cycle." (PMID 36545327, 2022).
Ewing sarcoma (1 paper, 2024). A small round cell tumor that lacks morphologic, immunohistochemical, and electron microscopic evidence of neuroectodermal differentiation. "And inhibiting MALAT1 in a METTL3-dependant manner suppresses cell migration and invasion in Ewing's sarcoma through miR-124-3p/CDK4 axis." (PMID 38355483, 2024). "Recently, researchers have observed higher levels of METTL3, ALKBH5, METTL14 and IGF2BP1 in chemotherapy-resistant OS cells, and METTL14 and YTHDF2 are associated with multiple drug sensitivity in Ewing's sarcoma." (PMID 38355483, 2024).